JAM2 (junctional adhesion molecule 2)
Description:
Junctional adhesion protein that mediates heterotypic cell-cell interactions with its cognate receptor JAM3 to regulate different cellular processes. Plays a role in homing and mobilization of hematopoietic stem and progenitor cells within the bone marrow. At the surface of bone marrow stromal cells, it contributes to the retention of the hematopoietic stem and progenitor cells expressing JAM3. Plays a central role in leukocytes extravasation by facilitating not only transmigration but also tethering and rolling of leukocytes along the endothelium. Tethering and rolling of leukocytes are dependent on the binding by JAM2 of the integrin alpha-4/beta-1. Plays a role in spermatogenesis where JAM2 and JAM3, which are respectively expressed by Sertoli and germ cells, mediate an interaction between both cell types and play an essential role in the anchorage of germ cells onto Sertoli cells and the assembly of cell polarity complexes during spermatid differentiation (By similarity). Also functions as an inhibitory somatodendritic cue that prevents the myelination of non-axonal parts of neurons (By similarity). During myogenesis, it is involved in myocyte fusion (By similarity). May also play a role in angiogenesis (By similarity).
Synonyms: JAM-B; JAM-2; VE-JAM; CD322; C21orf43; VEJAM; JAMB; IBGC8; PRO245
Tractability: Antibody: UniProt places it where antibodies can reach, with high confidence; its Gene Ontology location is reachable by antibodies, with high confidence; UniProt predicts a signal peptide or a membrane-spanning region; the Human Protein Atlas places it where antibodies can reach. PROTAC: ubiquitination databases record sites on it; its protein half-life has been measured.
Gene: Protein-coding gene on chromosome 21 (25,639,258 to 25,717,562, forward strand). Ensembl gene ENSG00000154721.
Subcellular location: Cell membrane; Cell junction; Cell junction, tight junction
Subcellular location (Human Protein Atlas): Plasma membrane; Nucleoplasm
Pathways (Reactome):
Extracellular matrix organization: Integrin cell surface interactions
Hemostasis: Cell surface interactions at the vascular wall
Gene Ontology:
Molecular function: integrin binding; protein binding
Biological process: cell-cell adhesion; cellular extravasation; hematopoietic stem cell migration to bone marrow; leukocyte tethering or rolling; lymphocyte aggregation; positive regulation of lymphocyte migration; leukocyte cell-cell adhesion; maintenance of blood-brain barrier; negative regulation of myelination; spermatid development
Cellular component: anchoring junction; cell surface; cell-cell contact zone; plasma membrane; protein complex involved in cell adhesion; somatodendritic compartment; tight junction; bicellular tight junction; cell-cell junction
Genetic constraint (gnomAD): Loss-of-function variants: 7 observed, 14.14 expected, observed/expected ratio (o/e) 0.5, 90% interval 0.28 to 0.93. The upper end of that interval is the gene's LOEUF score, 0.93, which puts it in group 3 of 6, group 1 being the genes least tolerant of losing a copy. Missense variants: 151 observed, 172 expected, observed/expected ratio (o/e) 0.88, 90% interval 0.77 to 1. Synonymous variants: 72 observed, 66.28 expected, observed/expected ratio (o/e) 1.09, 90% interval 0.9 to 1.32.
Homologues: Orthologues: macaque JAM2 (97% identical), chimpanzee JAM2 (97% identical), rabbit JAM2 (92% identical), pig JAM2 (88% identical), rat Jam2 (81% identical), dog JAM2 (80% identical), mouse Jam2 (77% identical), guinea pig JAM2 (75% identical), tropical clawed frog jam2 (52% identical), zebrafish jam2a (36% identical), zebrafish jam2b (34% identical). Paralogues in human: JAM3 (35% identical), F11R (32% identical), CXADR (23% identical), IGSF11 (23% identical), VSIG1 (21% identical), MXRA8 (20% identical), ESAM (19% identical), VSIG2 (19% identical), CLMP (19% identical), VSIG8 (19% identical), GPA33 (19% identical), VSTM2B (12% identical), and 2 more.
Diseases named in the same sentence as JAM2 in open-access papers:
JAM2 is named in the same sentence as 67 diseases in open-access papers, as found by Europe PMC text mining. Sharing a sentence is not in itself a finding about the gene and the disease. The quoted sentences say what the papers report.
breast carcinoma (10 papers, 2017 to 2025). "Overexpression of JAM2 blocks the invasion and migration of breast cancer cells by inhibiting the EMT pathway." (PMID 39247591, 2024). "The research of Yang shows that the overexpression of JAM-2 can block the invasion and migration of breast cancer cells." (PMID 36482887, 2022). "The expression level of JAM-2 in breast cancer is low, and the prognosis of patients with high expression of JAM-2 is good." (PMID 36482887, 2022). "Overexpression of JAM2 can block the invasion and migration of breast cancer cells, and the mechanism may be that JAM2 inhibits the Epithelial-Mesenchymal Transition pathway." (PMID 36482887, 2022). "In addition, overexpression of JAM2 could block the invasion and migration of breast cancer cells, and the mechanism might be that JAM2 inhibits the EMT process." (PMID 39838844, 2025). "In the TME of breast cancer, myCAFs were shown to promote an immunosuppressive environment by attracting and retaining CD4+CD25+ T-cells through the ligands tumor necrosis factor receptor superfamily member 4 (OX40L), PD-L2, and the adhesion molecule junctional adhesion molecule B (JAM2)." (PMID 36010901, 2022).
colorectal cancer (6 papers, 2015 to 2025). A primary or metastatic malignant neoplasm that affects the colon or rectum. "JAM‐2 expression levels were negatively correlated with colorectal cancer progression across multiple datasets." (PMID 39838844, 2025). "In colorectal cancer cells, reduced expression of JAM‐2 may lead to reduced intercellular adhesion, thereby increasing the migration and invasion ability of tumor cells." (PMID 39838844, 2025). "JAM-2 may function as a putative tumor suppressor in the progression and metastasis of colorectal cancer." (PMID 32231730, 2020). "JAM-2 may also function as a putative tumor suppressor in the progression and metastasis of colorectal cancer." (PMID 32231730, 2020). "Furthermore, we found that several genes coding for junctional adhesion molecules (JAM) (JAM2 and JAM3) have H3K4me3 peaks in normal colon cells but not in colorectal cancer cells." (PMID 40141189, 2025).
coccidiosis (4 papers, 2021 to 2025). A parasitic infection caused by Coccidia. "E. maxima challenge did not change the gene expression of other TJ proteins such as claudin-1, JAM-2, occluding, and ZO-1, most likely due to the fact that the challenge resulted in mild coccidiosis as determined by a lesion score of only 1.5." (PMID 35812452, 2022). "The depression of relative mRNA expression of JAM-2 and occludin observed during mixed Eimeria challenge in the current study is indicative of the impairment of the tight junction barrier due to sloughing of the intestinal epithelial cells and disruption of the mucus layer during coccidiosis." (PMID 41130050, 2025). "Moreover, elevated levels of ZO-1 and JAM-2 gene expression in chickens that were treated with higher dosages of B. subtilis-cNK-2 compared to control B. subtilis-EV demonstrated reduced damage by coccidiosis on gut barrier functions." (PMID 34150899, 2021). "Studies focusing on intestinal integrity in coccidiosis have found an increase in intestinal permeability and an upregulation of the tight junction proteins, claudin-1 (CLDN1), and junctional adhesion molecule-2 (JAM2) in a mixed-species Eimeria infection." (PMID 37680750, 2023).
glioma (4 papers, 2015 to 2025). A benign or malignant brain and spinal cord tumor that arises from glial cells (astrocytes, oligodendrocytes, ependymal cells). "JAM2 was upregulated significantly in tumor samples compared with adjacent normal tissues in gastric cancer, glioma, and human oral cancer." (PMID 39838844, 2025). "Blocking JAM2 and JAM3 in vitro impaired the growth and invasion of glioma cells, and their expression was increased in tumor cells." (PMID 25879740, 2015). "The complex of JAM2 and JAM‐C, which were paracrine stimuli from both tumor cells and endothelial cells, might promote glioma invasion by regulating cell migration and invasion through c‐Src, which is a proto‐oncogene." (PMID 39838844, 2025). "In order to explore whether this contradiction exists in gliomas, we compared the expression levels of vascular stability-related markers (ANGPT1, ANGPT2, JAM2, MCAM, PDGFRB, and VE-Cadherin) in the high- and low-score glioma groups in the TCGA, CGGA, and CGGA (array) datasets." (PMID 35579998, 2022).
colon cancer (3 papers, 2017 to 2022). "Lower expression of the tight junction protein-encoding gene JAM2 has been observed in colon tumors compared with normal specimens." (PMID 28257124, 2017). "According to the research of Zhao, the expression of JAM-2 in colon cancer cell line can reduce the growth, adhesion, migration and invasion of tumor cells." (PMID 36482887, 2022). "JAM2 is reported to be instrumental for metastatic progression in breast and colon cancer, while others are known regulators of migratory/invasive properties in many cancers." (PMID 31310629, 2019).
Down syndrome (3 papers, 2018 to 2025). "Notably, three genes outside of the deletions (JAM2, ADAMTS1, and ETS2) and within the Down syndrome critical region (DSCR) were downregulated in RD_P26 NESCs when compared to euploid NESCs." (PMID 35186010, 2021).
gastric cancer (3 papers, 2015 to 2020). A primary or metastatic malignant neoplasm involving the stomach. "Therefore, further biological experiments in vivo and in vitro are required to confirm the functions of OGN, JAM2, RERG, OLFML2B and ADAMTS1 genes in gastric cancer in the future." (PMID 33015704, 2020).
asthma (2 papers, 2020 to 2022). "These genes included RBM42, STX5, and TRIM41 in asthma, CYP27A1, GM2A, LGALS9, SPI1, and NLRC4 in COPD, ATF3, PPP1R15A, ZFP36, SOCS3, NAMPT, and GADD45B in IPF, LRRC48 and CETN2 in asthma-COPD, COL15A1, GIMAP6, and JAM2 in asthma-IPF and LMO7, TSPAN13, LAMA3, and ANXA3 in COPD-IPF." (PMID 31952466, 2020). "In addition, other identified genes were LRRC48 and CETN2 in asthma-COPD, COL15A1, GIMAP6, and JAM2 in asthma-IPF, along with LMO7, TSPAN13, LAMA3, and ANXA3 in COPD-IPF." (PMID 31952466, 2020). "Accordingly, COL15A1, GIMAP6, and JAM2 may present a novel therapeutic strategy for the asthma-IPF." (PMID 31952466, 2020). "Five novel hub DEGs (i.e., JAM2, SIGLECP3, C14orf186, COL15A1, and GIMAP6) were identified in asthma-IPF among ten hub DEGs." (PMID 31952466, 2020).
Ataxia (2 papers, 2021 to 2023). Ataxia refers to impaired coordination of voluntary muscle movement. "The patient with a homozygous JAM2 mutation developed ataxia at age 31, while the patient with a heterozygous PDGFB mutation developed dizziness and fever at 18 years old." (PMID 37237429, 2023). "Jam2-KO mice exhibited extensive reactive ACs, mild microglial activation, and reduction in neuronal density, as well as impaired motor coordination and gait disturbance in accordance with ataxia and parkinsonism in patients with PFBC." (PMID 33889180, 2021).
epilepsy (2 papers, 2023 to 2025). A brain disorder characterized by episodes of abnormally increased neuronal discharge resulting in transient episodes of sensory or motor neurological dysfunction, or psychic dysfunction. "These two epilepsy-susceptibility genes identified by PWAS were IQSEC1 (IQ motif and Sec7 Domain ArfGEF 1, chromosome 3), and JAM2 (junctional adhesion molecule 2, chromosome 21)." (PMID 37246165, 2023). "We identified five significant genes (WIPF1, IQSEC1, JAM2, ICAM3, and ZNF143) that had causal relationships with epilepsy." (PMID 37246165, 2023).
Fahr's disease (2 papers, 2020 to 2023). "Genes implicated in Fahr's disease include PDGFB, PDGFRB, SLC20A2, XPR1, MYORG, and JAM2." (PMID 37780723, 2023).
gastric adenocarcinoma (2 papers, 2022 to 2025). "Previous investigation also confirmed that JAM2 expression in stomach adenocarcinoma was significantly correlated with multiple tumor‐infiltrating immune cells." (PMID 39838844, 2025). "The Jam2 gene was found to be upregulated in gastric adenocarcinoma tissues." (PMID 35563241, 2022).
liver cancer (2 papers, 2017 to 2022). An epithelial or non-epithelial malignant neoplasm that arises from the liver. "Due to the lack of relevant literature on JAM-2 gene, its specific role in liver cancer needs further study." (PMID 36482887, 2022). "Using The Cancer Genome Atlas datasets to re-analyze the effect of some previously reported metastatic genes-e.g., JAM2, PPARGC1A, SIK2, and TRAF6-on overall survival of patients with renal and liver cancers, we found that these genes are actually protective factors for patients with cancer." (PMID 28372569, 2017).
lung adenocarcinoma (2 papers, 2022 to 2025). A carcinoma that arises from the lung and is characterized by the presence of malignant glandular epithelial cells. "The staining intensity of TNFSF14, JAM2, HGF, SPN, and LIFR in the tumors of 50 lung adenocarcinoma patients was first analyzed by immunohistochemistry and quantified according to H-scores." (PMID 36072807, 2022).
Parkinsonism (2 papers, 2021 to 2025). Characteristic neurologic anomaly resulting from degeneration of dopamine-generating cells in the substantia nigra, a region of the midbrain, characterized clinically by shaking, rigidity, slowness of movement and difficulty with walking and gait. "Notably, other related genes, such as “PDGFRB,” “MYORG,” “XPR1,” and “JAM2,” as well as phenotypic traits like “dementia” and “parkinsonism,” also exhibited significant node sizes." (PMID 40456615, 2025).
Cerebellar atrophy (1 paper, 2023). Cerebellar atrophy is defined as a cerebellum with initially normal structures, in a posterior fossa with normal size, which displays enlarged fissures (interfolial spaces) in comparison to the foliae secondary to loss of tissue. "Radiological patterns of calcium deposition are similar in all known genetic forms, but central pontine calcification and cerebellar atrophy are highly suggestive of MYORG mutations and extensive cortical calcification has been associated with JAM2 mutations." (PMID 36862146, 2023).
Chronic colitis (1 paper, 2023). A chronic inflammatory disease of the large intestine (colon, cecum and rectum). "Jam2 and Ocln mRNA expression was significantly increased in both wildtype and Muc13−/− mice upon acute and chronic colitis, respectively, whereas Tjp2 mRNA expression was only elevated in Muc13−/− mice after the first DSS cycle." (PMID 37174625, 2023).
colorectal tumors (1 paper, 2023). "In summary, our findings suggest that ZEB2, JAM2, NDN, and PPAP2A, along with the seven transcription factors related to these hub genes, may be associated with the response of colorectal tumors to chemoradiotherapy." (PMID 37636389, 2023).
esophageal neoplasm (1 paper, 2024). "As predicted by applying the CTD database, AKAP12 showed the highest association with esophageal neoplasm/esophageal squamous cell carcinoma, whereas JAM2 showed the lowest correlation." (PMID 39247591, 2024).
Hyperglycemia (1 paper, 2020). An increased concentration of glucose in the blood. "In the present study, hyperglycemic conditions induced JAM2 upregulation in hPSC-derived AOs, indicating that hyperglycemia-induced JAM2 expression might be conserved between murine animals and humans." (PMID 32932992, 2020). "Among the genes, junctional adhesion molecule 2 (JAM2) was found to be transcriptionally and epigenetically regulated by hyperglycemia." (PMID 32932992, 2020). "Notably, MSC-CM suppressed hyperglycemia-enhanced JAM2 expression in the lungs, suggesting that JAM2 could be a useful indicator for predicting the in vivo therapeutic outcomes of MSCs isolated from different donors and different tissue sites for diabetic lung fibrosis." (PMID 32932992, 2020).
leukemia (1 paper, 2010). A malignant (clonal) hematologic disorder, involving hematopoietic stem cells and characterized by the presence of primitive or atypical myeloid or lymphoid cells in the bone marrow and the blood. "For example, the TIM shows multiple eQTLs of JAM2 (junctional adhesion molecule 2) which was reported to be associated with leukemia in copy number variation studies." (PMID 21044360, 2010). "Our analysis indicates that the structural genetic variations can induce changes in expression of JAM2, which in turn may be a source of leukemia pathogenesis." (PMID 21044360, 2010).
liver fibrosis (1 paper, 2020). "Moreover, the upregulation of JAM2 and JAM3 by endothelial cells and de novo synthesis of JAM3 by hepatic stellate cells trigger autoimmune-mediated liver fibrosis in mice." (PMID 32932992, 2020).
myeloma (1 paper, 2014). "These include adhesion molecules such as JAM2 and JAM3 as well as CR2, the latter of which was shown to play a role in the interaction of myeloma cells with the bone marrow stroma." (PMID 25188243, 2014).
pelvic organ prolapse (1 paper, 2025). Abnormal descent of a pelvic organ resulting in the protrusion of the organ beyond its normal anatomical confines. "This study aimed to elucidate the roles of junctional adhesion molecule 2 (JAM‐2), collagen I and matrix metalloproteinase 2 (MMP‐2) in the pathogenesis of pelvic organ prolapse (POP) and explore their potential as diagnostic markers." (PMID 40159633, 2025). "Importantly, our study demonstrates the significant diagnostic potential of JAM‐2, Collagen I and MMP‐2 for pelvic organ prolapse (POP)." (PMID 40159633, 2025).
pseudohypoparathyroidism (1 paper, 2024). "Despite the thorough analysis, no known pathogenic variants were found in genes typically associated with Fahr’s syndrome (e.g., XRP1, PDGFRB, JAM2, PDGFB, SLC20A2, or MYORG) or pseudohypoparathyroidism (e.g., GNAS, STX16, or GNASAS1)." (PMID 39519162, 2024).
tongue cancer (1 paper, 2019). A malignant neoplasm affecting the tongue. "Differential expression profiling of the tongue cancer cohort triaged based on the stage, pathology identified multiple candidate markers; JAM2, SMURF1, LY6E, MFN1 and SUPT16H." (PMID 31310629, 2019).
type 1 diabetic (1 paper, 2020). "In type 1 diabetic mice, JAM2 and JAM3 have been reported to polarize leukocyte trans-endothelial migration and subsequently destruct insulin-producing beta cells in the pancreas." (PMID 32932992, 2020).
virus infection (1 paper, 2023). "The top 4 were “Cell matrix adhesion and organization” (COL6A1, COL6A2, COL18A1, JAM2, ADAMTS5 and POFUT2), “Immune/virus infection response” (MX1 and MX2), “Histone modification and chromatin remodeling” (NRIP1) and “Glycerolipid and lipid metabolism” (AGPAT3)." (PMID 38095646, 2023).